SSH1 (slingshot protein phosphatase 1)
Diseases named in the same sentence as SSH1 in open-access papers (continued):
Sharing a sentence is not in itself a finding about the gene and the disease.
tumor (continued). "In contrast, CFL-1 and SSH1 have expression downregulated in all tumor stages." (PMID 33482809, 2021). "The precise balance between expression and subcellular localization of CFL-1, LIMK1, and SSH1 is pivotal for small changes in the dynamics of the actin cytoskeleton, and may augment features of tumor aggressiveness, including tumor dissemination." (PMID 33482809, 2021). "Therefore, an analysis of the profile of gene and protein expression of CFL-1 and its regulators, LIMK1/SSH1, may provide important insights into the local invasion processes of primary tumor cells and could help in disease stratification in routine pathology." (PMID 33482809, 2021). "Our IHC profiling identified a direct association between CFL-1 and SSH1 levels with lymph node metastasis in CRC tissues, which was significantly correlated with lymph node metastasis risk by univariate analysis, supporting their role in local tumor dissemination." (PMID 33482809, 2021). "In the multivariate Cox regression model, tumor size (HR = 1.429, p = 0.007), lymphovascular invasion (HR = 1.692, p = 0.003), recurrence (HR = 3.856, p < 0.001), progression (HR = 2.655, p < 0.001) and SSH-1 positive expression (HR = 1.558, p = 0.015) were significant variables of CSS." (PMID 31965287, 2020). "However, in this study, SSH1 was expressed in GC tissue, and its expression level was positively correlated with tumour LNM and poor prognosis; multivariate regression analysis clearly indicated that SSH1 expression in GC tissues was an exceptional predictor of poor prognosis (P = 0.030)." (PMID 29338701, 2018). "Heterogeneous expression for CFL-1, SSH1 and LIMK1 were detected when tumor tissues were paired with adjacent normal samples." (PMID 33482809, 2021). "IHC quantification revealed high levels (0.8 median score) of SSH1 in stage III tumor tissues, while tissues in stages I, II, IV and in metastatic tissue revealed weak focally positive staining intensity in groups of tumor cells." (PMID 33482809, 2021).
bacterial infection (1 paper, 2014). "To decipher if SSH1 is involved preferentially in early or late events during the inflammatory response to S. flexneri, we measured IL-8 mRNA and IL-8 release at different time points after bacterial infection." (PMID 25187968, 2014).
immune disease (1 paper, 2021). "For example, variation in an ASD-related gene SSH1 (rs117900986, c.A1862G, p.N621S) was associated with the human immune disease." (PMID 33412999, 2021).
infection (1 paper, 2014). The state of being infected such as from the introduction of a foreign agent such as serum, vaccine, antigenic substance or organism. "Depletion of SSH1 mRNA by the two SSH1-specific siRNA duplexes resulted in significantly impaired IL-8 and IL-6 production 6 h post infection with the invasive S. flexneri strain M90T." (PMID 25187968, 2014). "Depletion of SSH1 led to greatly reduced IL-8 transcription as early as 30 min after infection." (PMID 25187968, 2014). "This validated that silencing of SSH1 significantly impaired NOD1-mediated responses in human cells triggered by TriDAP and infection with the invasive bacterial pathogen S. flexneri." (PMID 25187968, 2014). "Two hours post infection, when IL-8 became measurable in the supernatant of infected cells, a significant difference in IL-8 secretion was observed between cells treated with SSH1 targeting siRNA and those treated with a non-targeting control siRNA." (PMID 25187968, 2014).
neurodegenerative disease (1 paper, 2024). A disorder of the central nervous system characterized by gradual and progressive loss of neural tissue and neurologic function. "It is evident that the alternation of cofilin/p-cofilin dynamics and its upstream signaling cascades, such as SSH1 and LIMK, is involved in the pathophysiology of different neurodegenerative diseases." (PMID 38256947, 2024).
SSH1 also shares sentences with these, for which no sentence is quoted: Cerebral ischemia (1 paper); cholangiocarcinoma (1); digestive system tumours (1); Fibroadenoma (1); glioblastoma (1); head and neck squamous cell carcinoma (1); hepatocellular carcinoma (1); ischemia (1); liver cancer (1); lung carcinoma (1); melanoma (1); pancreatic cancer (1); paraganglioma (1); pheochromocytoma (1); prostate carcinoma (1); retinitis pigmentosa (1); thyroid cancer (1).